S100A4 (S100 calcium binding protein A4)
Diseases named in the same sentence as S100A4 in open-access papers (continued):
Sharing a sentence is not in itself a finding about the gene and the disease.
cancer (continued). "Further investigationsin well-characterized cancer cell lines with different S100A4 expressionlevels would be needed to confirm this activity and are the subjectof future work." (PMID 39425667, 2024). "In particular, MYH9 was shown to interact with the calcium-dependent S100 family member S100A4 to promote the motility of human cancer cells." (PMID 36797800, 2023). "It is unclear what types of cells in the lungs are responsible for S100A4 secretion; however, cell types like pulmonary artery smooth muscle cells, fibroblasts, and several cancer cells have been identified to secrete S100A4." (PMID 37873538, 2023). "In the pathogenesis of cancer, increased S100A4 expression correlates with a high incidence of metastasis and poor prognosis in cancer." (PMID 36895491, 2023). "Cancer-associated fibroblast (CAF) sub-clusters showing high expression of IL6, CCL2, S100A4, PDPN, and FGF7 were identified in both primary and metastatic samples." (PMID 38328306, 2023). "High S100A4 mRNA expression accurately predicted poor survival for patients with CRC independently of cancer type." (PMID 36895491, 2023). "In cancer cell lines, the levels of S100A4 transcript were on average higher (mean Ct = 5.31 +/− 2.99) than those of other S100s, with large variations being observed between cell lines." (PMID 37627239, 2023). "For the 20% elastin hydrogel, results showed that various biomarkers, including myofibroblast cell markers (α-SMA, THY-1) and cancer-associated markers (PDGF-β, S100A4), were involved in the FMT." (PMID 37848974, 2023). "Current studies on S100A4 have mainly focused on its role in regulating tumorigenesis and cancer metastasis." (PMID 37873538, 2023). "Specifically, LINC01833 can promote these activities by modulating the MiR-519e-3p/S100A4 axis and has shown promise as a biomarker for predicting cancer patient prognosis." (PMID 38011277, 2023). "As a versatile enforcer of cancer progression and metastasis, S100A4 is a stage-independent predictor for metachronous metastasis in CRC and other solid tumor entities." (PMID 36008464, 2022). "S100A4 is the downregulated gene in DHM-treated cells and there are some reports regarding S100A4 and cancer metastasis." (PMID 36499426, 2022). "S100A4 is a calcium-binding protein belonging to the S100 family of proteins and contributes to the metastasis of different cancer." (PMID 35965620, 2022). "S100A4 interacts with the Wnt/β-catenin pathway to modulate cell migration in cancer and fibrotic diseases." (PMID 35154161, 2022). "An example is represented by the regulation of acidic calcium-binding protein S100A4 overexpression, which has been correlated with DNA hypomethylation in several cancers, including LSCC." (PMID 35406495, 2022). "S100A4 has been demonstrated in the development of an aggressive metastatic phenotype progressing into cancer and metastasis." (PMID 35965620, 2022). "Remarkably, in cancer cell lines S100A4 interacts with cytoskeletal proteins as well as with focal adhesion proteins such as Talin." (PMID 35277137, 2022). "We discovered that through β-catenin signaling, MACC1 directly induces S100A4 expression and secretion, and further mediates MACC1 pro-migratory effect on cancer cells through S100A4 as the enforcing molecule." (PMID 36008464, 2022). "Other work demonstrated that S100A4 (Mts1) plays different roles in cancer progression depending on the different circumstances." (PMID 35546077, 2022). "In several types of cancer cells, S100A4 is responsible for their ability to form metastases, promoting their invasiveness." (PMID 35805957, 2022).
cancer (continued). "One of these proteins, extracellular S100A4, has been shown to play unusual roles in cancer progression that are very similar to the roles of HMGB1 and S100A8/A9." (PMID 36142212, 2022). "CAFs express fibroblast activation protein-alpha (FAPα), smooth muscle actin alpha (α-SMA), PDGF receptor alpha (PDGFRα), PDGF receptor beta (PDGFRβ), and/or fibroblast specific protein 1 (FSP-1/S100A4), depending on the type of cancer." (PMID 35986369, 2022). "Adlay polysaccharides targeting S100A4 are an alternative cancer chemotherapy, and inhibit migration and invasion of A549 cells by downregulation of S100A4, as well as possibly interacting with the binding site of S100A4-NMIIA." (PMID 35956759, 2022). "This is in accordance with several animal studies using DEN/CCl4-induced HCC, or human cancer cells xenografts, and consistently showing that S100a4 promotes cell proliferation, invasion and metastasis dissemination." (PMID 36232334, 2022). "We were able to demonstrate that circulating transcripts of MACC1 and S100A4 are detectable in blood of cancer patients and serve as reliable biomarkers for OS and MFS." (PMID 36008464, 2022). "Numerous studies have already revealed roles of S100A4 in cancer progression, particularly the ability of enhancing metastasis." (PMID 35305619, 2022). "Increased expression levels of S100A4 were observed in various types of cancers; thus, S100A4 is a key driver of tumorigenesis and metastasis." (PMID 35214097, 2022). "S100A4 has proven to be a valuable biological marker and therapeutic target for many types of cancer." (PMID 36235175, 2022). "As some mesenchymal signature genes, for example S100A4, were upregulated in cancer cell in the scRNA-seq analysis, we assumed that the cancer cells underwent activate EMT." (PMID 36307773, 2022). "S100A4 has been extensively studied in cancer studies including colorectal, breast, lung and liver cancers." (PMID 36078170, 2022). "Therapeutic approaches to reduce S100A4 expression, and thereby restrict cancer progression and metastasis, including RNA interference (RNAi) and small molecules for intervention strategies in the Wnt pathway." (PMID 35008201, 2021). "On the contrary, it has also been reported that EMT is amplified by the overexpression of S100A4 in cancer cells." (PMID 33994540, 2021). "S100A4 protein is one of the most extensively studied S100 family members, which is now considered as a valuable biomarker for cancer diagnosis and metastasis prediction." (PMID 34650982, 2021). "The expression of known cancer-related genes such as Sostdc1, S100a4, Crabp2, and Id3 was significantly upregulated in the cancer stem-like cell cluster." (PMID 34785704, 2021). "Upregulation of several of these genes, for instance, PTPRZ1, WNT5A, S100A4, or ANXA1/2, has been linked to cancer invasion and aggressiveness in some solid tumors, including GBM25–30." (PMID 34112916, 2021). "Down-regulation or neutralization of S100A4 in the CM of mtPC3 cells attenuated cancer-induced osteoclastogenesis." (PMID 33549040, 2021). "For example, upregulating the expression of S100A4 promotes cancer metastasis and correlates with poor prognosis of multiple cancers." (PMID 34124754, 2021). "Remarkably, in recent years, the relationship between S100A4 overexpression and cancer stem cells has become clearer." (PMID 33805347, 2021). "Especially, S100A4 has been shown to be overexpressed in various cancer, including breast and pancreatic cancer leading to its nickname “Metastatin”." (PMID 34572138, 2021). "Accumulating evidence supports the role of S100A4 as a crucial determinant of mesenchymal transition in various types of cancer cells." (PMID 33549040, 2021). "Out of all S100A family members, S100A4 has the most pronounced and best investigated function in the regulation of cancer cell migration and metastasis." (PMID 34209679, 2021). "Increased protein expression of S100A4 correlates with a high incidence of metastasis and poor prognosis in cancer." (PMID 34209679, 2021).
cancer (continued). "Lastly, the epithelial to mesenchymal transition (EMT) is a key event during cancer progression, and S100A4 has been reported to participate actively to mediate such transition." (PMID 33805347, 2021). "In vivo and in vitro experimental studies showed the over-expression of one subgroup of S100, S100A4, related to potential metastatic and poor clinical outcomes in different kinds of cancers." (PMID 33507685, 2021). "Several novel genes including Sostdc1, S100a4, Crabp2, and Id3 were identified among the top upregulated genes in the cancer stem-like cell population." (PMID 34785704, 2021). "Neutrophils can directly induce proliferation of cancer cells through the secretion of NE, S100A4, S100A8/A9, FGF2, HGF, BMP2, TGFβ2 and transferrin." (PMID 34572138, 2021). "S100A4 is specific S100 family metastasis-related protein, which is upregulated in many cancer tissues and cell lines, where it controls cell proliferation, differentiation and metastasis." (PMID 32842846, 2020). "S100A4 belongs to a large family of EF-hand domain calcium-binding proteins and has become a recognized marker of cancer metastasis in S100 transcripts." (PMID 32596158, 2020). "We also detected enrichment for transcripts encoding fibroblast-specific protein 1 (FSP1/S100a4), keratins Krt7, Krt8, Krt14 and Krt18 and claudins Cldn3, Cldn4 and Cldn7 in this cluster which were also enriched in epithelial/cancer cells." (PMID 32455670, 2020). "S100A4 is a member of calcium binding S100 protein family well known for its role in cancer progression and metastasis." (PMID 32021963, 2020). "As two independent studies have reported a role for these chaperones in the sensitivity/resistance to treatment of different types of cancer, the similarity of S100A4 and TBCA profiles in rat spleen in the context of MM progression is intriguing." (PMID 32290283, 2020). "The multifaceted roles of S100A4 in the development of cancer have been identified in plenty of studies." (PMID 32307910, 2020). "By binding to extracellular partners like annexin A2 and transglutaminase-2, S100A4 can also hinder cell-ECM adhesion of cancer cells." (PMID 31652274, 2019). "The role of S100A4 in controlling cell proliferation, cancer invasion, and metastasis has been extensively studied in numerous laboratories (PMID: 9703888)." (PMID 31608231, 2019). "Increased levels of S100A4 were reported for several tumors and it also correlates with worse prognosis in cancer patients." (PMID 31652274, 2019). "A direct coculture of cancer cells and pre-osteoclasts also showed reduced osteoclast formation by S100A4 knockdown in mtMDA cells." (PMID 31667000, 2019). "In several types of cancer cells, S100A4 is responsible for their capability to form metastases, promoting their motility and invasiveness." (PMID 31623154, 2019). "The presence of S100A4 has now been demonstrated in cancers (e.g., pancreatic gastric, colorectal, bladder, and breast)." (PMID 30779808, 2019). "Targeting S100A4 by small interfering RNA led to decreased expression of matrix metalloproteinase 2 and 9, and reduced proliferation and invasiveness of cancer cells." (PMID 30970087, 2019). "Next, we explored the relationship between S100A4 levels in these cancer cells and the osteoclastogenic effects of cancer cell CM." (PMID 31667000, 2019). "The elevated secretion of S100A4 from bone-metastatic mtMDA cells and the stimulation of osteoclastogenesis by S100A4 led us to next investigate the in vivo relevance of S100A4 in the bone destruction induced by bone-metastasized cancers." (PMID 31667000, 2019).
cancer (continued). "S100A4, belonging to a large multifunctional S100 protein family, is a Ca2+-binding protein with a significant role in stimulating the motility of cancer and immune cells, as well as in promoting pro-inflammatory properties in different cell types." (PMID 31623154, 2019). "In this paper we have demonstrated that S100A4 expression can indeed modulate tissue-level contractility of epithelial carcinoma cells in vitro." (PMID 31652274, 2019). "Previous research has shown that inhibition of S100a4 expression in cancer cell lines suppressed cell invasion in vitro." (PMID 29910813, 2018). "We have recently discovered that IPF MPCs and their early generation progeny highly express S100A4, a calcium-binding protein also expressed by cancer stem cells, as well as some immune cells." (PMID 28860143, 2018). "Immunohistochemistry (IHC) and immunofluorescence staining for CD133 as well as other cancer-associated proteins, including cytokeratin 19, TGF-β1, p-Smad2 and epithelial–mesenchymal transition (EMT) markers S100A4, E-Cadherin and Vimentin were analyzed." (PMID 29510695, 2018). "Specific knockdown of S100A4 resulted in cell responses in human GC and other cancer cells, such as decreased proliferation, migration, and invasion." (PMID 29342841, 2018). "After S100A4 knockdown in cancer cells, certain genes that inhibit proliferation and migration (e.g., FAM107B and E-cadherin) were upregulated, while those genes that normally promote proliferation and migration (e.g., NF-κB, p65 and MMP2) were downregulated." (PMID 29342841, 2018). "Extracellular S100A4 has been reported to provide a driving force to cancer cells in the metastatic process by stimulating motility of cancer cells and by activating endothelial cells, leading to enhanced angiogenesis." (PMID 30041429, 2018). "Its overexpression correlates with poor patients’ prognosis; high S100A4 levels are prognostic for metachronous metastases formation and correlate with reduced patient survival in several cancer types." (PMID 29544454, 2018). "The increase in four multifunctional proteins, prohibitin and prohibitin 2, annexin A5 and protein S100A4, has also been documented in cancers, contributing to tumorigenic processes such as cell proliferation, metastasis, angiogenesis and immune evasion." (PMID 29662647, 2018). "We found by a pull-down assay that embigin is a novel receptor for S100A4, which is one of the vital cancer microenvironment milleu." (PMID 30041429, 2018). "A growing number of studies have demonstrated the direct involvement of S100A4 in cancer progression and metastasis." (PMID 29204268, 2017). "S100A4, an important member of the S100 family of proteins, is best known for its significant role in promoting cancer progression and metastasis." (PMID 29204268, 2017). "This section discusses and reviews up-to-date information on S100A4 in different human common malignant tumors." (PMID 29069865, 2017). "The molecular mechanisms of S100A4 involving in the progression and metastasis are diverse in various malignant tumors." (PMID 29069865, 2017). "Validation of S100A4 as a biomarker in early cancer detection and prediction of prognosis and treatment responses; 2)." (PMID 29069865, 2017). "More importantly, an improved knowledge in S100A4 expression and cancer biology can further potentiate the emergence of new targeted therapies." (PMID 26903691, 2016). "Surprisingly, the GEFs fared better as prognostic markers than two established markers of cancer progression, S100A4 and MACC1." (PMID 26916336, 2016). "Enhanced cell growth and motility upon elevated S100A4 expression increases the metastatic potential of cancer cells originating from many entities, like breast, lung, prostate, bone, and cancers from the digestive tract, in vitro and in mice." (PMID 27331819, 2016).
cancer (continued). "When focusing on the molecular mechanisms of S100A4 and its role in cancer, a number of cancer related protein-protein interaction partners have been described, including cytoskeletal proteins such as actin, myosin, and tropomyosin." (PMID 27331819, 2016). "Previous studies show that S100A4 is a direct β-catenin/TCF target and highly associated with metastasis and poor survival in cancer patients." (PMID 27793047, 2016). "There was no significant variation in BM staining for the S100 proteins by primary cancer (Fisher's exact test for S100P, P=0.279, and S100A4, P=0.135)." (PMID 27100728, 2016). "In a previous study, extracellular S100A4 specifically activates NF-κB in several human cancer cell lines via the classical NF-κB pathway." (PMID 27679610, 2016). "S100A4 expression levels in tumors are considered as a biomarker for the prognosis of both metachronous metastasis and survival of cancer patients." (PMID 27331819, 2016). "The expression level of S100A4 in tumors of cancer patients also correlates with enhanced progression and metastasis formation, emphasizing its importance in clinical cancer diagnosis." (PMID 27331819, 2016). "S100A4 expression has been implicated to the metastatic potential of cancer cells and a correlation between the expression of S100A4 and the metastatic state and prognosis was shown for several cancer entities." (PMID 26741489, 2016). "S100A4 is known to promote aggressive behavior in human cancers and can be induced by cigarette smoke [Monzon ME, et.al., Am J Resp Crit Care." (PMID 27127879, 2016). "S100A4 is secreted by both cancer and stromal cells to participate in both paracrine and autocrine signaling through its putative receptor RAGE, as well as through EGFR- and Toll-like receptor-4 (TLR-4)-mediated pathways." (PMID 27127879, 2016). "The protein S100A4 is known to regulate cell cycle progression, intercellular adhesion, invasion and metastatic properties of the cancer cells." (PMID 27561007, 2016). "S100A4, a member of the S100 protein family, is involved in a broad range of biological functions as well as in the regulation of migration and invasion of cancer cells." (PMID 26741489, 2016). "Increased S100A4 expression has been identified in different human cancers, and previous reports indicated a relationship between the expression of S100A4 and poor prognosis." (PMID 27559743, 2016). "On the one hand, S100A4 is commonly found upregulated in various kinds of cancer cells, including PC cells." (PMID 26903691, 2016). "We have shown that S100A4 interacts with Rhotekin to facilitate the formation of cell membrane protrusions and promote invasive growth in carcinoma cells." (PMID 27127879, 2016). "Therefore, soluble human S100A4 protein and its mAbs may be used as tools for further functional investigations into S100A4 and for the improvement of diagnostic and therapeutic strategies in cancer treatment." (PMID 25339497, 2015). "Taking into account its pivotal role in metastasis, S100A4 was suggested as a potential target for a novel cancer therapy." (PMID 25884510, 2015). "In the present report, S100A4 was upregulated in MDA-MB-231 cancer cells under conditions of low cell density, minimal FBS supplementation, HS, and when cells are grown in a DMEM formulation." (PMID 25776572, 2015). "Transwell migration and invasion assays demonstrated an increased number of cells in the experimental group compared with that in the control group, thus indicating that the recombinant S100A4 protein promoted the motility and invasiveness of cancer cells." (PMID 25339497, 2015). "Studies on the role of S100A4 have mainly focused on the invasive growth and metastasis of numerous types of cancer." (PMID 25339497, 2015). "S100A4 is expressed in many human cancers, and is correlated with poor prognosis and an elevated incidence of metastasis." (PMID 25884510, 2015).